IL1B (interleukin 1 beta)
Diseases named in the same sentence as IL1B in open-access papers (continued):
Sharing a sentence is not in itself a finding about the gene and the disease.
myocardial infarction (384 papers, 2008 to 2026). Gross necrosis of the myocardium, as a result of interruption of the blood supply to the area, as in coronary thrombosis. "Recent studies have shown that targeting IL-1β with drugs like canakinumab reduces the risk of cardiovascular events in patients who have had a heart attack." (PMID 40283183, 2025). "The IL-1β inhibitor canakinumab significantly reduced the first major adverse cardiovascular event and residual inflammatory risk in patients with previous myocardial infarction (MI)." (PMID 40287718, 2025). "Pivotal clinical trials such as Canakinumab Anti-inflammatory Thrombosis Outcomes Study (CANTOS) have shown that targeting inflammation through IL-1β inhibition reduces the risk of myocardial infarction and stroke independently of lipid levels." (PMID 41464678, 2025). "For this reason, IL-R2 and other receptors functionally linked to IL-1β are expected to be recruited following an inflammatory event such as myocardial infarction." (PMID 39184952, 2024). "Elevated IL-6 levels were significantly associated with peripheral artery disease, myocardial infarction, and heart failure, while IL-1β levels were linked to worse outcomes in coronary artery disease and heart failure." (PMID 39057626, 2024). "A recent study that integrated multiple MI scRNA-seq datasets further revealed that macrophages regulate myofibroblast activation through the secretion of TGF-β1, TNF, and IL-1β, which are associated with myocardial infarction fibrosis." (PMID 39632841, 2024). "In patients with myocardial infarction, increased levels of IL-1B are associated with worse cardiac outcomes." (PMID 38535084, 2024). "He showed that increased IL-1B levels at 2 months following myocardial infarction were associated with the left ventricle end systolic index." (PMID 38535084, 2024). "Meanwhile, CPC has a positive effect against acute myocardial infarction, causing down-expression of phospho-(Ser 536)-NFκB p65 and mRNA synthesis for IL-1β, IL-6, TNF-α, and INFγ." (PMID 39000141, 2024). "In the CANTOS-trial canakinumab, an IL-1β antibody, in patients with myocardial infarction and active inflammation resulted in less all-cause mortality and a lower rate for HF hospitalization." (PMID 35548445, 2022). "In the CANTOS trial (Canakinumab Anti-Inflammatory Thrombosis Outcomes Study), the treatment of patients with previous myocardial infarct with the monoclonal IL-1β-neutralizing antibody canakinumab reduced the risk of recurrent cardiovascular events." (PMID 34977191, 2021). "The CANTOS trial has shown that treatment with the monoclonal IL-1β-neutralizing antibody canakinumab can reducing the risk of recurrent cardiovascular events in patients with prior heart attack." (PMID 34803503, 2021). "For instance, the results of the Canakinumab Anti-Inflammatory Thrombosis Outcomes Study demonstrate that treatment with monoclonal IL-1β-neutralizing antibody canakinumab reduces the risk of recurrent cardiovascular events in patients with prior heart attack." (PMID 34658858, 2021). "Recently, the CANTOS trial showed that targeted cytokine inhibition (IL-1β inhibition with Canakinumab) in CAD patients with a prior myocardial infarction and residual inflammatory risk reduced further cardiovascular events." (PMID 32647892, 2021). "CANTOS was a randomized, double-blinded, placebo-controlled trial that investigated the use of canakinumab, a monoclonal antibody targeting IL-1β, on high-risk patients with established atherosclerotic disease who had survived a myocardial infarction (MI)." (PMID 34539627, 2021). "Endothelial-specific overexpression of MYC was sufficient to induce type H bone endothelial cells, whereas inhibition of NLRP3-dependent IL-1β production partially prevented the post-myocardial infarction loss of type H vasculature in mice." (PMID 34172720, 2021). "Il1b gene polymorphisms influence the risk of myocardial infarction and ischemic stroke at a young age through NF-κB, iNOS, MMP-2 and Bax." (PMID 31827539, 2019).
myocardial infarction (continued). "In humans, anti-inflammatory treatments targeting TNFα or IL-1β are associated with decreased risk of myocardial infarction and overall cardiovascular events." (PMID 31461490, 2019). "In myocardial ischemia, serum levels of IL-1β are increased, and they cause the activation of the myofibroblasts involved in cardiac remodeling and the alteration of systolic function after acute myocardial infarction." (PMID 31205590, 2019). "Imbalance between IL-1 and IL-1Ra has been shown to determine the degree of cardiac remodeling after myocardial infarction, and a high IL-1Ra/IL-1β ratio is associated with a better outcome in patients after traumatic brain injury." (PMID 26860727, 2016). "In a human case-control study, the -511T single nucleotide polymorphism (SNP) in IL1B was associated with a lower release of IL-1B from human mononuclear cells and a relatively low risk of myocardial infarction at young age." (PMID 22768033, 2012). "IL-1β—and to a lesser extent IL-18—was elevated in adult cardiac cases, suggesting partial necroptosis activation during sterile cardiac stress, as has been previously implicated in myocardial infarction and ischemia–reperfusion injury." (PMID 40722817, 2025). "The hydroalcoholic extracts of aerial parts of A. italica exhibited significant anti‐inflammatory potentials shown by down‐regulation of TNF‐α, IL‐1β, and IL‐6 in myocardial infarction mice model, which were mainly linked with its total flavonoid and polyphenolic contents." (PMID 39723071, 2024). "The major clinically concluded CANTOS study tested the therapeutic effect of the anti-IL-1β antibody, Canakinumab, in a group of patients after myocardial infarction, and showed 31% reduction in cardiovascular and all-cause mortality in certain, but not all, groups of patients." (PMID 37539090, 2023). "The importance of IL1β was shown also in a large clinical trial where a monoclonal antibody against IL1β reduced the rate of recurrent cardiovascular events in patients that sustained a prior myocardial infarction and showed residual inflammatory risk as assessed by C-reactive protein levels." (PMID 34017863, 2021). "Also, experimental myocardial infarction in Wistar rats and levels of cardiac IL-1β, IL-6, and IL-2 were associated with antiapoptotic and anti-inflammatory mechanisms by compound 21, and compound 21 prevented vascular inflammation in vitro and in vivo." (PMID 34220496, 2021). "Administration of anti-IL-1β monoclonal antibody reduced the relative risk of major adverse cardiovascular events by up to 25%, in addition to the 31% decline in cardiovascular and overall mortality in patients with a history of myocardial infarction." (PMID 33291425, 2020). "Considering that IL-1β polymorphism might modulate an inflammation-triggered pathway, the implication of -511C/T IL-1β polymorphism has been studied in myocardial infarction, ischemic stroke, hypertension, atherogenesis, and thrombosis." (PMID 31052244, 2019). "In a murine myocardial infarction model, reduced M2 macrophage content was associated with increased M1-related gene expression (IL-6 and IL-1β), and decreased M2-related gene expression (Arginase1 and CD206) in the heart of GW2580-treated animals versus vehicle-treated controls." (PMID 26407006, 2015). "In myofibroblasts, NLRP3 inflammasome activation can cause the increase of activated IL-1β, which ultimately stimulates collagen synthesis, extracellular matrix protein expression, and myofibroblast differentiation, and participates in myocardial fibrosis and scar repair after myocardial infarction." (PMID 35401934, 2022). "Many studies have reported that the IL-1β + 3954C/T polymorphism (rs1143634) is related to myocardial infarction (MI)." (PMID 30045312, 2018). "For instance, the CANTOS trial demonstrated reduced recurrent major adverse cardiovascular events by using anti-IL-1β antibody in treating stable cardiovascular patients post-myocardial infarction, along with standard care." (PMID 41544081, 2026).
myocardial infarction (continued). "Colchicine blocks the assembly of the NLRP3 inflammasome, thereby reducing its activation and the release of proinflammatory cytokines such as interleukin-1β (IL-1β) and IL-18, key molecules in amplifying the inflammatory response after myocardial infarction." (PMID 41511355, 2025). "After myocardial infarction, IL-1β is upregulated and promotes adverse cardiac remodeling while also negatively affecting the β-adrenergic pathway and promoting myocyte dysfunction." (PMID 40564905, 2025). "The crucial role of IL-1β in acute myocardial infarction (AMI) and heart failure (HF) has been verified via preclinical and clinical investigations." (PMID 39811465, 2025). "Of these agents, the IL-1β inhibitor canakinumab proved to be effective at MACE rate reduction in patients with previous myocardial infarction and elevated C-reactive protein levels." (PMID 41303445, 2025). "The individual roles of IL-1α vs. IL-1β in the setting of acute myocardial infarction (AMI) and CKD were investigated in patients and knockout mice deficient for IL-1α vs. IL-1β." (PMID 40486517, 2025). "As a key molecule in regulating cell pyroptotic necrosis, the absence of GSDMD reduces the degree of myocardial fibrosis after myocardial infarction, and decreases IL-1β released by infiltrating myeloid cells in the heart, thus playing a cardioprotective role." (PMID 40176832, 2025). "In patients with prior myocardial infarction and elevated CRP, the IL-1β inhibitor, canakinumab, reduced cardiovascular event risk and the levels of IL-6 and CRP but did not affect LDL cholesterol and showed a small increase in fatal infections." (PMID 40564905, 2025). "Canakimumab, a monoclonal antibody targeting IL-1β, reduced cardiovascular events in patients with previous myocardial infarction and a CRP >2 mg/L, but increased infection-related deaths." (PMID 40796058, 2025). "Studies have found that mice with myocardial infarction experience a decrease in left ventricular ejection fraction and increased expression of IL-1β, IL-18, and IL-10-mRNA after sleep deprivation." (PMID 40644492, 2025). "Literature reports that pretreatment with the NLRP3 inhibitor INF195 can significantly inhibit IL-1β production, thereby reducing inflammation and significantly decreasing the myocardial infarction area." (PMID 40486827, 2025). "In the CANTOS study, which was conducted on patients with a history of myocardial infarction, the administration of monoclonal antibodies to IL-1β (Canakinumab) resulted in fewer adverse cardiovascular events relative to patients receiving a placebo." (PMID 41303445, 2025). "Interleukin (IL)-1β, a key mediator of the inflammatory response following myocardial infarction (MI), has been demonstrated to directly and synergistically compromise cardiac contractility." (PMID 39811465, 2025). "Previous research showed that CoQ10 can alleviate inflammation partially via inhibiting the NLRP3/IL‐1β pathway to promote the recovery of cardiac function after myocardial infarction." (PMID 40951583, 2025). "In summary, we provide exciting evidence that neutrophil NLRP3 exacerbates myocardial infarction (MI) injury in the early phase through the local release of NETs and IL-1β." (PMID 38914598, 2024). "Clinical trials have demonstrated that IL-1β inhibitors, such as canakinumab, significantly reduce recurrent myocardial infarction and other major adverse cardiovascular events." (PMID 39057626, 2024). "Overall, these data support the central role of attenuated IL1β signaling in CoQ10-mediated inflammation reduction after myocardial infarction." (PMID 38281937, 2024). "A study reported that miR-132 can target IL1B in myocardial infarction to inhibit apoptosis of myocardial cells, further demonstrating the potential of IL1B as a target for apoptosis intervention and a biomarker." (PMID 39650552, 2024).
myocardial infarction (continued). "A randomized control trial called CANTOS (Canakinumab Anti-inflammatory Thrombosis Outcome Study) with over 10 thousand patients with previous myocardial infarction received different doses of canakinumab, a monoclonal antibody for IL-1β, or placebo." (PMID 38256155, 2024). "The Canakinumab Anti-inflammatory Thrombosis Outcome Study (CANTOS) study showed the benefit of canakinumab, an IL-1β blockade, in patients with previous myocardial infarction." (PMID 38203796, 2024). "Controlling IL-1β-mediated inflammation is important because it has been shown that the blockade of IL-1 signaling reduces damage from heart failure following acute myocardial infarction in humans." (PMID 38543157, 2024). "A nice study by Orn on patients following myocardial infarction evaluated the correlation between IL1-B and the EF values at different time points." (PMID 38535084, 2024). "This has been stimulated by the beneficial, lipid-independent effects of IL-1β blockade on cardiovascular outcome in patients with a previous myocardial infarction and high hs-CRP levels in the CANTOS trial." (PMID 39717783, 2024). "Canakinumab Anti-inflammatory Thrombosis Outcome Study revealed that the deactivating cytokine IL-1β reduced inflammation and cardiovascular death in myocardial infarction patients." (PMID 38441007, 2024). "The CANTOS trial, which demonstrated that canakinumab (an IL-1β inhibitor) significantly reduced recurrent cardiovascular events in patients with a history of myocardial infarction, highlights the potential benefits of such therapeutic approaches." (PMID 39057626, 2024). "The inflammasome trans and IL-1β cytokines play critical roles in cardiovascular diseases like atherosclerosis, myocardial infarction (MI), myocarditis, and heart failure (HF)." (PMID 39766086, 2024). "The CANTOS trial, for example, showed that canakinumab, an IL-1β inhibitor, significantly reduced recurrent cardiovascular events in patients with a history of myocardial infarction." (PMID 39057626, 2024). "In the CANTOS trial, canakinumab (an IL-1β targeting antibody) reduced the number of major cardiovascular events in CKD patients with a prior myocardial infarction and high inflammatory (CRP) status." (PMID 38416185, 2024). "In the CANTOS trial, canakinumab, a monoclonal antibody targeting the IL-1β innate immunity pathway, significantly reduced the incidence of recurrent cardiovascular events in patients with myocardial infarction." (PMID 38402392, 2024). "The CANTOS trial was a double-blind, randomized study investigating the effects of canakinumab, a monoclonal antibody against the proinflammatory cytokine IL-1β, in patients with recent myocardial infarction (MI)." (PMID 39199336, 2024). "The inflammatory response during myocardial infarction is regulated by several inflammatory markers, including IL-1β, iNOS, NF-κB, and TLR4." (PMID 39211776, 2024). "MCC950 is a selective NLRP3 inhibitor that, in several animal models, has been shown to decrease IL-1β production, reduce atherosclerotic plaque size, and reduce the infarct area in experimental models of myocardial infarction." (PMID 36983163, 2023). "The recent CANTOS trial demonstrated that canakinumab, an IL-1β-targeting antibody, reduces the recurrence of cardiovascular events in patients with a previous myocardial infarction." (PMID 37894840, 2023). "NLRP3, IL-1β, IL-18, and hsCRP levels were significantly higher in myocardial infarction patients compared to the healthy group (p = 0.02, p < 0.001, p < 0.001, and p < 0.001, respectively)." (PMID 37763063, 2023). "Drugs that antagonize the actions of IL-1β have demonstrated benefits in reducing cardiovascular events in patients with prior myocardial infarction." (PMID 36383638, 2023). "Further, the Canakinumab Anti-inflammatory Thrombosis Outcome Study (CANTOS) showed that in patients with a previous myocardial infarction concomitant with systemic inflammation, IL-1β inhibition reduced coronary disease." (PMID 36891247, 2023).